RAD51 (RAD51 recombinase)
Diseases named in the same sentence as RAD51 in open-access papers (continued):
Sharing a sentence is not in itself a finding about the gene and the disease.
breast cancer (continued). "Breast carcinoma cells submitted to hypoxia (0.01% O2) showed a decrease in H3K4 methylation (H3K4me2,3), associated with increased transcriptional activity in BRCA1 and RAD51 promoter regions, and, therefore, presented a decreased expression of these genes." (PMID 30939818, 2019). "However, BP significantly inhibited the expression levels of Rad51 in a dose-dependent manner in both breast cancer cell lines." (PMID 29370116, 2018). "BRCA1/2 breast cancer proteins are key players in HR via their mediation of RAD51 nucleofilament formation and function; however, their individual roles and crosstalk in vivo are unknown." (PMID 30250272, 2018). "We therefore examined the expression of Ku70, Ku80, and Rad51 by western blot to assess whether these two pathways were altered in BP-treatment breast cancer cells." (PMID 29370116, 2018). "For example, considering that AUC > 0.75 supports good biomarker feasibility, ENAH and RAD51 could be repurposed for breast cancer diagnosis usage." (PMID 29050243, 2017). "Previous studies have shown elevated RAD51 expression levels in prostate cancer, invasive breast cancer and small cell lung cancers; however, decreased RAD51 expression levels in breast tumors and breast cancer cell lines have also been reported." (PMID 27513445, 2016). "However, in this study, we provide the first evidence that RAD51-induced hyper-recombination is a mechanism of drug resistance in both normal mammary epithelial cells and a breast cancer cell line." (PMID 27513445, 2016). "Moreover, in prostate and breast cancer, high RAD51 protein levels appear to be consistent with tumor progression and resistance to therapy." (PMID 27495836, 2016). "Based on BRCA1 and RAD51 knockdown expression profiles and primary breast tumor expression data, we provide a computational method to infer the cell proliferation level for each breast cancer patient." (PMID 27788678, 2016). "In literature, neither XRCC2-41657C/T nor RAD51-172G/T polymorphism is correlated with risk of breast cancer." (PMID 25743260, 2015). "Further, in other study demonstrated that BARD1 and RAD51 are frequently overexpressed in BMs from breast cancer and may constitute a mechanism to overcome reactive oxygen species-mediated genotoxic stress in the metastatic brain." (PMID 25559688, 2015). "Moreover, we found that IGF-1Rki affects HR in ovarian and breast cancer cells by reducing the expression of RAD51 at the mRNA level, and this subsequently decreased RAD51 protein level and its interaction with IRS-1." (PMID 26510816, 2015). "In RAD51, only intronic and UTR variants were identified which is in line with the previous studies where no cancer-predisposing mutations were identified among early-onset breast cancer patients." (PMID 25918678, 2015). "However, one of the detected 5’UTR polymorphisms, rs1801320, has been found to affect the splicing of RAD51 within the 5’UTR and to modify breast cancer risk among BRCA2 mutation carriers." (PMID 25918678, 2015). "Forty-seven were excluded as they were not relevant to the aim of our study (association of RAD51 135G > C with breast cancer)." (PMID 26108708, 2015). "Taken together, this data suggest that RAD51 targeting might be important in HER2-positive breast cancer." (PMID 25559688, 2015). "The absence of mutations in our study as well as the results of the previous studies indicates that XRCC3 and RAD51 are not major breast cancer susceptibility genes." (PMID 25918678, 2015). "In the reported study, the 135G/C but not 172G/T polymorphism, of RAD51 gene, was associated with breast carcinoma occurrence." (PMID 25743260, 2015).
breast cancer (continued). "Overall in silico revealed similar RAD51 expression trends to those observed with cell lines and patient immunohistochemistry, consistent with the notion that RAD51 expression is increased during breast cancer progression and metastasis, suggesting an oncogenic role when deregulated." (PMID 24811120, 2014). "Paradoxically, Rad51 is overexpressed in multiple tumor types, including breast cancer." (PMID 24811120, 2014). "Overall, these data indicate that RAD51 overexpression might have significant impact on progression and metastasis of breast cancer." (PMID 24811120, 2014). "BRCA2 and Rad51 expression were proposed as histologic criteria in canine breast cancer staging." (PMID 24641873, 2014). "For example, overexpressed miR-155 could reduce the efficiency of DNA repair and enhance radiosensitivity of breast cancer cells by directly repressing RAD51." (PMID 25026294, 2014). "It is reasonable to assume that RAD51 and BRCA1/2 mutations may have interactive effects on breast cancer risk." (PMID 24040396, 2013). "Taking the similarity and close association between XRCC3 and RAD51 into account, it is speculated that XRCC3 may also play an important role in the pathogenesis of breast cancer." (PMID 23977219, 2013). "It is known that RAD51 expression is significantly increased in breast cancer." (PMID 23977219, 2013). "Some previous studies presented an association of RAD51 variant allele 135C with an elevated breast cancer risk only in BRCA2 mutation carrier, but not in BRCA1 mutation carriers or non-carriers or unselected populations." (PMID 24040396, 2013). "Base on these results, we are disposed to agree that overexpression of XRCC3 and RAD51 may play an important role in the pathogenesis of breast cancer." (PMID 23977219, 2013). "At the germline level, some studies have shown that the single nucleotide polymorphism (SNP) −135G>C (rs1801320) in the 5′ untranslated region (UTR) of RAD51 modifies breast cancer risk in BRCA2 mutation carriers but not in BRCA1 mutation carriers." (PMID 23300655, 2012). "Other RAD51 gene family members had been associated with increased risk of breast cancer, but there had been no reports implicating RAD51C." (PMID 21980511, 2011). "Ma and colleagues detected an increase in RAD51 mRNA expression in Ductal Carcinoma In Situ-Invasive Ductal Carcinoma transition and high-tumour-grade breast cancers, while it has also been found that overexpression of RAD51 correlates with histological grading of Invasive Ductal Carcinoma." (PMID 16762046, 2006). "Four studies have investigated the coding region of RAD51 for variation in breast cancer to date." (PMID 16762046, 2006). "Alteration in either the expression or protein structure of RAD51 could therefore have similar deleterious effects on these essential pathways, leading to breast cancer." (PMID 16762046, 2006). "Additionally, lymphoblastoid cell lines from breast cancer patients were subjected to single nucleotide primer extension analysis to assess RAD51 expression." (PMID 16762046, 2006). "Besides the interactions of RAD51 with key players in breast tumourigenesis, there is additional evidence to support a role for RAD51 in breast cancer." (PMID 16762046, 2006). "In contrast to HTATSF1/Wt and HTATSF1/S748D, HTATSF1/S748A mutation could not efficiently rescue HTATSF1 depletion-induced defects, upon cisplatin and irradiation treatment, including TOPBP1 recruitment and RAD51 loading at γH2AX-marked damaged chromatin in EdU-labeled S-phase breast cancer cells." (PMID 38762174, 2024). "However, a contrary observation was made in breast cancer, in which it was revealed that miR-155-5p decreased the efficiency of homologous recombination repair and enhanced sensitivity to radiation by targeting RAD51 directly." (PMID 36980974, 2023).
breast cancer (continued). "Finally, our findings suggest that RB may affect HR by interacting with key protein members of HR repair (such as RAD51) in breast cancer cell lines." (PMID 34932500, 2022). "However, an increase in RAD51, a gene involved in homologous recombination that is regulated by YAP1, is the only reported underlying mechanism explaining how YAP1 regulates DNA damage repair induced through cisplatin in breast cancer." (PMID 34689211, 2022). "However, the knockdown of RAD51 decreased the metastatic potential of breast cancer." (PMID 32190537, 2020). "Also, no mutations were detected for other described breast cancer‐associated genes (e.g., RAD51, RAD50, p27, ESR1/2, ERBB2, ERBB3, AKT1, CCDN1, FGFR1, MYC, and RB1) in any of the tissues or the CTC cell line." (PMID 32667137, 2020). "Moreover, a high expression of RAD51 may be a significant prognostic marker in breast cancer, glioblastoma, and esophageal squamous cell carcinoma." (PMID 31973027, 2020). "The joint effect of RAD51 rs1801321 and XRCC3 rs861539 (HR pathway) on cancer risk has been previously reported for breast cancer, in line with our results, and may be of particular relevance for DTC since the formation of radiation damage-induced RAD51 foci requires functional XRCC3." (PMID 31374908, 2019). "Indeed, it has been reported that the BRIP1 and RAD51 pathogenic variants confer at least a 6-fold increased risk for OC, but not for breast cancer, in contrast to the NBN and CHEK2 genes." (PMID 30441849, 2018). "Studying RAD51-foci formed ex vivo has been used as a functional assay to determine the genetic HR-status of breast cancer tissue indirectly, and we therefore tested whether this assay can be used on bladder cells to determine the effects of hyperthermia on HR." (PMID 30550547, 2018). "Clinically, this could be very important as low RAD51 levels have been associated with favorable response after chemotherapy in breast cancer patients, due to the lack of repair following DNA damaging therapies." (PMID 30100993, 2018). "Furthermore, we demonstrated for the first time that BP could radiosensitize human breast cancer cells to radiation by increasing DNA damage, and the down-regulation of the homologous recombination repair protein, Rad51." (PMID 29370116, 2018). "In breast cancer, PG could activate apoptosis by different signaling pathways including reducing Wnt/β-catenin, c-Jun N-terminal kinases/p38/RAD51 (JNK/p38/RAD51), or glycogen synthase kinase 3 beta/NAG-1 (GSK-3β/NAG-1), and inducing endoplasmic reticulum (ER) stress." (PMID 30282915, 2018). "However, the expression of these up-regulated ones were decreased once pyrvinium pamoate was added, among which several (breast cancer susceptibility gene (BRCA2), DNA ligase IV (LIG4) as well as recombinase RAD51) exhibited significantly decreased P-values as compared with doxorubicin alone group." (PMID 27303922, 2016). "Interestingly, the depletion or chemical inhibition of PAK in PAK1 amplified or overexpressing breast cancer cells treated with DNA damaging agents, compromised the ability of these cells to form Rad51 foci, induced cell cycle arrest, promoted apoptosis and resulted in reduced colony formation." (PMID 27740936, 2016). "Thus, the targeting of RAD51, PARPi and p38 also may have the ability to prevent metastatic dissemination of breast cancer cells and this forms part of our ongoing investigations." (PMID 27507046, 2016). "In conclusion, the absence of mutations among breast cancer families and similar distribution of haplotypes between breast cancer cases and controls suggests that RAD51, XRCC3, and XRCC2 do not substantially contribute to familial breast cancer predisposition in the Finnish population." (PMID 25918678, 2015). "The contribution of RAD51, XRCC3, and XRCC2 to breast cancer susceptibility remains unclear." (PMID 25918678, 2015).
breast cancer (continued). "We screened the RAD51, XRCC3, and XRCC2 genes for germline variation in familial BRCA1/2-negative breast or ovarian cancer patients in order to evaluate the role of these genes in breast cancer predisposition in Finland and to identify putative recurrent founder mutations." (PMID 25918678, 2015). "Since about 65% of the studies included in this meta-analysis were undertaken on Caucasian subjects, further studies on East Asians may be required to confidently rule out the association of RAD51 135G > C substitution with breast cancer in these populations." (PMID 26108708, 2015). "In the RAD51 gene, one possibly disease-associated missense mutation has been identified in bilateral breast cancer patients whereas three studies report no deleterious RAD51 mutations among breast cancer cases." (PMID 25918678, 2015). "Moreover, dysregulation of RAD51 expression in breast cancer cells has been reported." (PMID 23300655, 2012). "Our study indicates that RAD51 is not a major familial breast cancer predisposition gene." (PMID 16762046, 2006). "Schmutte and colleagues screened the RAD51 coding region and the surrounding intron/exon boundaries in 41 breast carcinomas (family history unknown) by SSCP but found no mutations." (PMID 16762046, 2006). "This study reveals that BCKDK can localize within the nuclei of breast cancer cells, where it binds to and phosphorylates RNF8, thereby inhibiting the ubiquitin‐mediated degradation of RAD51." (PMID 40298908, 2025). "This study has demonstrated that BCKDK localizes to breast cancer cell nuclei, where it binds to and phosphorylates RNF8, thereby blocking ubiquitin‐mediated degradation of RAD51 and enhancing HRR." (PMID 40298908, 2025). "In ER + breast cancer, methylation of BRCA2 partially inhibits RAD51, resulting in increased RAD51 expression and resistance to AIs." (PMID 40949156, 2025). "Western blot employed to determine the expression of endogenous HCN2, HCN3, BRCA1, BRCA2, and RAD51, confirmed that either HCN2 or HCN3 was overexpressed in the breast cancer cells, whilst HEK293 had low expression in both of HCN2 and HCN3." (PMID 40764992, 2025). "As a nuclear transport protein, KPNA2 is involved in the cytoplasmic retention of key DNA damage response proteins including BRCA1, RAD51, and CHK1 in breast cancer cells." (PMID 40002266, 2025). "Similar to RAD51, HRD was more prevalent in ovarian cancer (83.3% [15 of 18]) than in breast cancer (50.0% [5 of 10])." (PMID 38648056, 2024). "Based on the data gathered, we propose, for the first time, that SOC therapies used in ER+ breast cancer reduce the expressions of DNA repair proteins, XRCC1, FEN1, BRCA1, BRCA2 and RAD51, caretakers in maintaining genomic integrity." (PMID 37914699, 2023). "PRMT5 expression was moderately to strongly correlated (Pearson score ≥ 0.4) with established DDR genes such as BRCA1, BRCA2, RAD51, RAD51D, RAD51AP1, FANCA, and FANCI across 125 ovarian and breast cancer cell lines." (PMID 37861290, 2023). "The human RAD51 gene, located on chromosome 15q15.1, is considered to participate in a common DSB repair pathway and is involved in the development of breast cancer development." (PMID 36761956, 2023). "Our study’s primary aim was to evaluate the association of common putatively functional SNPs in HRR genes NBN, RAD51, and XRCC3 with RT adverse events in patients with early HER2-positive breast cancer treated with adjuvant RT." (PMID 36139526, 2022). "Increased expression of HR-related molecules, such as RAD51 and BRCA2, has also been observed in canine mammary tumor tissue, but their functional roles in tumor cell lines have not been investigated." (PMID 36548864, 2022). "Amplification and overexpression of RAD51C, a paralog of RAD51, has been demonstrated in breast cancer cell lines including MCF-7 and a subset of primary breast cancer samples." (PMID 36428789, 2022).
breast cancer (continued). "In breast cancer stem cells (bCSCs), BMI1 has been located to stalled replication forks to recruit Rad51 and activate HRR pathways, whereas BMI1 cannot activate HRR pathways in non-bCSCs." (PMID 35875146, 2022). "The breast cancer suppressor BRCA2 and the RAD51 paralog complexes, either RAD51B–RAD51C–RAD51D–XRCC2 (BCDX2) or RAD51C–XRCC3 (CX3) then help load RAD51 on the resected DNA to form a filament, displacing RPA." (PMID 35801922, 2022). "Although RAD51 overexpression in normal HDF and breast cancer cells markedly disrupted genomic integrity, no impact on cell cycle was observed in these cell types." (PMID 36428789, 2022). "Disruption of the interaction between RAD51 and BRCA2 leads to genomic instability and the development of mammary tumors." (PMID 36548864, 2022). "We overexpressed RAD51 in normal (normal human diploid fibroblasts; HDF), EAC (FLO-1) and breast cancer (MDA-MB-231) cells and investigated the impact on cell cycle using flow cytometry." (PMID 36428789, 2022). "The overexpression of RAD51 was related to higher tumor grade and characteristics of aggressive tumors (e.g., lack of hormone receptor expression and HER2 amplification) in breast cancer." (PMID 36233194, 2022). "Consistent with this, we here demonstrate that elevated RAD51 expression correlates with poor survival in EAC, colon and breast cancer patients." (PMID 36428789, 2022). "VPA inhibited the protein expression of Rad51 and BRCA1 upon IR treatment in those breast cancer cell lines, which was consistent with the finding in the transformed cells." (PMID 33842359, 2021). "Using a well-established breast cancer rat model induced by DMBA, the RFWD3-dependent Rad51 ubiquitination involved in the VPA-mediated bidirectional effect under RT was also confirmed." (PMID 33842359, 2021). "Currently an oral RAD51 inhibitor CYT-0851 is being tested in a Phase 1/2 study against relapsed/refractory B-cell malignancies and advanced solid tumours including breast cancer (NCT03997968)." (PMID 34316709, 2021). "Meanwhile, to confirm the effect of VPA on malignant cells, we also tested the expression of Rad51 and BRCA1 in several breast cancer cell lines including MCF7, MDA-MB-231, and EUFA423." (PMID 33842359, 2021). "Through DMBA-transformed breast cancer rat model, VPA at 200 mg/kg radiosensitized tumor tissue cells by increasing RFWD3 and inhibited Rad51, while radioprotected normal tissue cells by decreasing RFWD3 and enhanced Rad51." (PMID 33842359, 2021). "In summary, the ATM/ZEB1/USP7/CHK1, miR-200c/LINC02582/USP7/CHK1, USP7/PHF8, UCHL3/RAD51, USP52/ASF1A, and UCHL1/HIF-1 signaling axis are potential targets to improve the radiosensitivity of breast cancer." (PMID 34575114, 2021). "For example, AKT silencing restored formation of IR-induced BRCA1 foci in breast cancer cells, whereas HR-related proteins (e.g., BRCA1 and Rad51) sequestered in the cytoplasm upon activation of AKT1." (PMID 33266502, 2020). "Another group also reported Rad51-mediated resistance to PARP inhibition in triple negative breast cancers and breast cancer stem cells." (PMID 32405340, 2020). "RAD51 interacts directly with XRCC2, XRCC3, and breast cancer genes (BRCA1 and BRCA2) to form a complex that is essential for double-strand break repair." (PMID 32316696, 2020). "Hypoxia has also been linked to downregulation of DNA damage response proteins such as RAD51 in prostate cancer, and RAD51 and BRCA1 in breast cancer, respectively." (PMID 30930892, 2019). "Since RAD51 is the downstream effector repair protein in FA-BRCA pathway-mediated HR, we evaluated its expression in breast cancer patients included in the TCGA database using the UALCAN portal." (PMID 31492187, 2019). "Present study revealed significant down-regulation of cell cycle and DNA damage response genes, including E2F1, E2F2, RAD51, and CCNB1 in breast cancer cells treated with palbociclib." (PMID 31548560, 2019).